CD164 (CD164 molecule)
Diseases named in the same sentence as CD164 in open-access papers (continued):
Sharing a sentence is not in itself a finding about the gene and the disease.
breast carcinoma (3 papers, 2013 to 2025). "Together, these findings demonstrate that CD164 inhibition has a potent anti-tumor effect by causing both cell cycle arrest and death in breast cancer cells." (PMID 40692786, 2025). "Aberrant Wnt signaling has been implicated in breast cancer metastasis, and our findings suggest CD164 may modulate this pathway to influence cell proliferation." (PMID 40692786, 2025). "Furthermore, inhibited by downregulation of CD164 expression was breast cancer cell proliferation and activity; it also caused cell cycle arrest and encouraged death." (PMID 40692786, 2025). "In this study, we utilized these two breast cancer cell lines to investigate the biological function of CD164." (PMID 40692786, 2025). "CD164 was highly expressed in breast cancer tissues and correlated with poorer prognosis, including shorter disease-free and overall survival." (PMID 40692786, 2025). "Female nude mice were given subcutaneous injections of SKBR3 cells to create a xenograft model of breast cancer, so validating the biological role of CD164 in vivo." (PMID 40692786, 2025). "Pan-cancer analysis established CD164 as both a prognostic marker across eight malignancies and specifically in breast cancer, where high expression correlated with significantly worse disease-free survival (DFS) and overall survival (OS)." (PMID 40692786, 2025). "In this study, we investigated the functional relevance of siRNA-mediated knockdown of CD164 in breast cancer cells by means of CCK-8, EdU incorporation, and colony development assays, so evaluating cell viability, proliferation, and clonogenicities." (PMID 40692786, 2025). "CD164 plays a critical role in breast cancer progression, influencing tumor growth, immune evasion, and therapeutic response." (PMID 40692786, 2025). "Analyzing drug response data from the GDSC database in early breast cancer samples allowed us to evaluate the possible function of CD164 in modulating chemosensitivity." (PMID 40692786, 2025). "Further analyses revealed a strong correlation between the M stage of breast cancer patients and CD164 expression levels." (PMID 40692786, 2025). "Analysis of mRNA expression data across multiple cancer types using the Pan-Cancer database revealed that tissue of breast cancer has CD164 greatly overexpressed." (PMID 40692786, 2025). "RNA sequencing was conducted to clarify the CD164 regulatory systems in breast cancer cell proliferation even more." (PMID 40692786, 2025). "The findings showed that in breast cancer cells, CD164 silencing greatly lowered both cell viability and proliferative capacity." (PMID 40692786, 2025). "Two specific small interfering RNAs that target CD164 were created to find out what role CD164 plays in these two types of breast cancer cells." (PMID 40692786, 2025). "The role of CD164 in breast cancer is still unclear, despite its growing significance in cancer biology, underscoring the need for further study." (PMID 40692786, 2025). "The TCGA database was used to assess CD164 expression in breast cancer and its correlation with prognosis." (PMID 40692786, 2025). "When combined, these findings suggest that CD164 may be a biomarker for the detection, management, and prognostic assessment of breast cancer." (PMID 40692786, 2025). "This work explored the function of CD164 in breast cancer by means of bioinformatics analyses." (PMID 40692786, 2025). "Aiming for CD164 could provide a fresh approach for tailored treatment plans for breast cancer patients." (PMID 40692786, 2025). "In conclusion, CD164 might be a biomarker for estimating the sensitivity of chemotherapy for breast cancer." (PMID 40692786, 2025). "Therefore, this work intends to investigate the molecular function of CD164 in this context and the correlation between CD164 expression and breast cancer." (PMID 40692786, 2025).
breast carcinoma (continued). "Future studies will focus on identifying the molecular mechanisms through which CD164 accelerates the development of breast cancer, paying special attention to its interactions with significant oncogenic signaling pathways and elements of the tumor microenvironment." (PMID 40692786, 2025). "However, studies on the function of CD164 in breast cancer are few." (PMID 40692786, 2025). "Though the link between CD164 and cancer stem cells is still poorly known, new data points point to their possible therapeutic target, especially in HER2-positive breast cancer subtypes." (PMID 40692786, 2025). "Significant overexpression of CD164 in SKBR3 cells was found by transcriptomic studies comparing the SKBR3 and MDA-MB-231 breast cancer cell lines, so suggesting its function in the course of breast cancer." (PMID 40692786, 2025). "Male and female breast cancers displayed remarkably different landscapes of candidate drivers, as only two candidate drivers were found in common (TAF4 and CD164)." (PMID 24194916, 2013). "Our screen assessed several known CD markers and identified several novel (i.e. CD63, CD98 and CD164) and less characterised (i.e. CD46, CD107a and CD321) breast epithelial markers, of which are overexpressed in at least 5% of breast cancer samples in the COSMIC database." (PMID 34120626, 2021).
glioblastoma (3 papers, 2019 to 2025). The most malignant astrocytic tumor (WHO grade IV). "For instance, there was a significant drop in CD164 expression and its network connections at 12-h stage, which aligns with its known role in glioblastoma proliferation." (PMID 40413377, 2025). "Mounting evidence indicates that CD164 contributes to stemness and tumorigenesis in normal cells and is overexpressed in various tumor types, including glioblastoma." (PMID 31007847, 2019). "Depletion of CD164 expression in human glioblastoma cells with siRNA reduced proliferation, migration, and invasiveness." (PMID 31007847, 2019).
lung carcinoma (3 papers, 2017 to 2019). "Emerging evidence indicates that elevated CD164 expression is associated with aggressive metastasis, advanced stages, and shorter overall survival in lung cancer." (PMID 28903328, 2017). "To identify the involvement of the CD164 on the spheroid cell formation from lung cancer cell lines, we cultured H2122 and CL 1-5 cells under stem cell growth medium in 96-well plates via the limiting dilution method." (PMID 28903328, 2017). "Among the three lung cancer cell lines, the expressed CD164 levels of H661 and H1299 cells were higher than BEAS2BWT, while the expressed CD164 level of A549 cells were lower than BEAS2BWT." (PMID 28903328, 2017). "Compared with BEAS2BWT, we performed the Western blot analysis to examine the expression of CD164 in three lung cancer cell lines, including H661, H1299, and A549." (PMID 28903328, 2017). "Using tissue microarrays, we determine that CD164 expression is correlated with clinicopathological characteristics in human lung cancer." (PMID 28903328, 2017). "CD164 was mainly expressed in the cytoplasm and membrane of normal lung tissues and lung cancer tissues." (PMID 28903328, 2017). "In H661 and H1299 lung cancer cells, Western blot analysis demonstrated that diminished CD164 expression resulted in decreased Akt and mTOR phosphorylation, and decreased CXCR4 activation." (PMID 28903328, 2017). "Different lung cancer cells, including adenocarcinoma, squamous cell carcinoma, large cell carcinoma, and small cell lung cancer, exhibited significantly higher mean CD164 H-scores than normal lung cells." (PMID 28903328, 2017). "However, no data are available regarding the clinical significance of CD164 expression in lung cancer." (PMID 28903328, 2017). "The model described here provided the CD164 expression in lung tumorigenic cancer-initiating cells may represent a key therapeutic strategy for future lung cancer treatment." (PMID 28903328, 2017). "In case of lung cancer patients with chemoresistance and high expression of CD164, therapeutic targeting of mTOR might be considered as an alternative potential therapy." (PMID 28903328, 2017). "Hence, CD164 might be the potential molecule to develop as a new therapeutic target for lung cancer." (PMID 28903328, 2017). "Therefore, identification of CD164 as a cancer stem cell therapeutic marker may develop an effective therapy in patients with chemoresistant lung cancer." (PMID 28903328, 2017). "We investigate whether the functional roles of CD164 promote lung tumor-initiation and drug resistance through the Akt/mTOR axis, as the clinical significance of CD164 expression in lung cancer has not been reported to date." (PMID 28903328, 2017).
non-small cell lung carcinoma (3 papers, 2020 to 2025). A group of at least three distinct histological types of lung cancer, including non-small cell squamous cell carcinoma, adenocarcinoma, and large cell carcinoma. "In non-small cell lung cancer, too, CD164 activates mTOR or ABC transporter signaling pathways to promote tumor initiation and chemoresistance." (PMID 40692786, 2025). "Moreover, aiming at CD164 can improve the radiosensitivity of non-small cell lung cancer cells." (PMID 40692786, 2025).
Hearing impairment (2 papers, 2015 to 2021). A decreased magnitude of the sensory perception of sound. "In conclusion, we have identified a new DFNA locus located on chromosome 6q15-21 and implicated CD164 as a novel gene for hearing impairment." (PMID 26197441, 2015). "Intriguingly, a mutated form of CD164 seems to be associated with hearing loss." (PMID 34399625, 2021). "To estimate the frequency of CD164 mutations among patients with unknown cause of hearing impairment, we sequenced all coding exons and splice junctions of CD164 using DNA samples from 46 independent index cases." (PMID 26197441, 2015). "The gene encodes CD164, a small transmembrane sialomucin protein involved in adhesion, migration and endocytosis and we provide data on the variant-, gene-, and functional level implicating the gene in hearing impairment." (PMID 26197441, 2015). "In conclusion we have identified a novel locus for hearing impairment with LOD score 5.1 and identified CD164 as the most likely causative gene in the locus." (PMID 26197441, 2015). "However, no sequence variants likely to cause hearing impairment were found, suggesting that mutations in CD164 are not a common cause of NSHI." (PMID 26197441, 2015).
viral infection (2 papers, 2022 to 2025). "In our measurements, a protein with an extracellular domain of ~200 amino acids (e.g. CD164 [138aa]) at a density of ~100 μm–2 showed significant inhibition in viral infection." (PMID 41147561, 2025). "Together, this study identifies novel factors associated with LCMV infection of human tissues and highlights the importance of CD164, a sialomucin that previously had not been associated with viral infection." (PMID 35502904, 2022). "Pseudotyped viral infection shows that CD164 is an LCMV-specific mammarenavirus human entry factor." (PMID 35502904, 2022).
acute lymphoblastic leukemia (1 paper, 2025). Leukemia with an acute onset, characterized by the presence of lymphoblasts in the bone marrow and the peripheral blood. "Additionally, CD164 can be used to diagnose anaphylaxis and acute lymphoblastic leukemia." (PMID 40692786, 2025).
bladder tumor (1 paper, 2018). "Taken together, we suspected that CD164 could promote the migration and invasion of bladder tumor cells through regulating relevant proteins including MMP2 and MMP9." (PMID 30022623, 2018).
brain tumor (1 paper, 2019). "We propose that CD164 may serve as a GBM molecular marker and a potential target in therapeutic strategies aimed to improve outcomes for this devastating brain tumor." (PMID 31007847, 2019).
HCMV infection (1 paper, 2021). "Since congenital HCMV infection is the leading infectious cause of hearing loss, it is tempting to speculate that CD164 might be a central player in the processes underlying HCMV pathogenesis." (PMID 34399625, 2021). "This is further emphasized by the fact that CD164 is expressed in all cell types tested and downregulated upon HCMV infection." (PMID 34399625, 2021). "Altogether, we decided on three hit candidate receptors: CD164, which was downregulated from the surfaces of all cells analyzed, and CD84 and CD180, which seem to be myeloid cell-specific receptors with reduced expression upon HCMV infection." (PMID 34399625, 2021).
heart failure (1 paper, 2021). Inability of the heart to pump blood at an adequate rate to meet tissue metabolic requirements. "To get the robust gene signature in heart failure, we overlapped genes from LASSO and SVM-RFE and got six gene signatures, including PALLD, DDX39A, CD164, CLDND1, SLC38A2, and CALU." (PMID 34926621, 2021).
lung adenocarcinoma (1 paper, 2017). A carcinoma that arises from the lung and is characterized by the presence of malignant glandular epithelial cells. "At least, two studies showed that higher CD164 mRNA expression in patients with lung adenocarcinoma and squamous cell lung cancer might significantly correlate with worse overall survival (HR =2.13; HR =1.68) in the five Kaplan-Meier survival curves from PRECOG database." (PMID 28903328, 2017).
metastatic tumors (1 paper, 2018). "The results suggested that the metastatic tumors in CD164 shRNA group were obviously smaller than controls (P < .05)." (PMID 30022623, 2018).
Niemann-Pick disease, type C1 (1 paper, 2017). Type C Niemann-Pick disease associated with a mutation in the gene NPC1, encoding Niemann-Pick C1 protein. "These were the genes encoding for Galactosidase A (GLA), Scavenger receptor class B member 2 (SCARB2), Niemann-Pick disease, type C1 (NPC1) and the CD164 molecule (CD164)." (PMID 29238336, 2017).
osteoarthritis (1 paper, 2022). A noninflammatory degenerative joint disease occurring chiefly in older persons, characterized by degeneration of the articular cartilage, hypertrophy of bone at the margins and changes in the synovial membrane. "Human skeletal stem cells (hSSCs) were recently identified as podoplanin (PDPN)/CD73/CD164-positive and CD146-negative cells that decline with age, and play a role in the pathogenesis of osteoarthritis (OA)." (PMID 35743928, 2022).
ovarian tumor (1 paper, 2013). "Our findings indicated that a high abundance of CD164 protein was only significantly correlated with high-grade ovarian tumors (P < 0.001)." (PMID 24094005, 2013). "Based upon these observations, we hypothesized that CD164 plays important roles in ovarian tumor growth in vivo." (PMID 24094005, 2013). "We further addressed whether the SDF1α/CXCR4 axis is involved in CD164-induced ovarian tumor growth." (PMID 24094005, 2013).
Salmonella Infections (1 paper, 2018). Infections with bacteria of the genus SALMONELLA. "On the other hand, FOXO signaling (TNFSF10, PRKAB1, GADD45B, STK4, STAT3), Salmonella infection (ARPC2, ARPC5L, CCL3L3, CCL4) and lysosome (LAPTM4B, HGSNAT, CD164, ATP6V0A2) pathways were up-regulated, albeit weakly, in the HLA-DR- Teff subset." (PMID 30231065, 2018).
Sézary syndrome (1 paper, 2023). "CD164 has been identified as a dependable marker for the specification of Hematopoietic Stem/Progenitor cells and as a potential therapeutic target for Sézary syndrome." (PMID 38020758, 2023).
urothelial bladder carcinoma (1 paper, 2018). "The object of our study was to investigate the functions of CD164 in urothelial bladder carcinoma." (PMID 30022623, 2018).
cancer (20 papers, 2006 to 2026). A tumor composed of atypical neoplastic, often pleomorphic cells that invade other tissues. "Activated EBF1 can upregulate target gene CD164, which is a cancer-promoting gene associated with tumorigenesis involved in the regulation of cell proliferation and adhesion." (PMID 31126066, 2019). "Taken together, these results underscore the significant role CD164 plays in regulating stemness, metastasis, and tumor cell growth across multiple cancer types." (PMID 40692786, 2025). "Zinc oxide nanoparticles regulate the proliferation and invasion of cancer by means of miR-506-3p/CD164 signaling and are used to target cancer stem cells." (PMID 40142941, 2025). "Recent research has shown that CD164 is essential for hematopoiesis as well as for the growth and invasion of malignant tumors, so promoting tumor progress." (PMID 40692786, 2025). "MiR-1271-5p was shown to negatively regulate CD164 expression, and inhibit cancer cell proliferation, migration, invasion, and the EMT90." (PMID 36927770, 2023). "We report widespread and consistent changes in alternative splicing of cancer-associated genes including CENPE, ESCO2, CKAP2, MELK, ASPH and CD164 in both HeLa and PC3 cells." (PMID 33846420, 2021). "Studies have found that CD164 overexpression promotes cancer cell migration by activating the CXCR4/PI3K/AKT/mTOR axis." (PMID 31007847, 2019). "Conversely, some genes that displayed anti-HIV activity are known to be involved in signaling, both in various cancers (CD164, TNFRSF10A/D, ZWINT, MT1X, IL3) and immune or T cell activation (GBP5, CD1A)." (PMID 25980612, 2015). "To examine the transforming effect of CD164 in non-cancer cells, such as hOSE, we overexpressed the CD164 gene and evaluated the effect of its overexpression on the cell morphology, proliferation, adhesion and anchorage-independent colony formation." (PMID 24094005, 2013). "CD164 has been proven to be highly expressed in hematopoietic stem cells and other stem cells and to be involved in some instances of cancer cell metastasis to other sites." (PMID 24094005, 2013). "The elucidation of the cis-regulatory elements is useful in understanding CD164 functions in cancer cells." (PMID 21999799, 2011). "To mimic this phenomenon in vitro, we explored the effect of CD164 on the ability of cancer cells to invade reconstituted extracellular matrix in response to CXCL12." (PMID 16859559, 2006). "The number of cancer cells exhibiting perinuclear and cytoplasmic expression of CD164 ranged from 90–100% in PC3 and LNCaP C4-2B cells." (PMID 16859559, 2006). "By focusing on CD164, immunotherapy’s efficacy may be raised, and the immune system’s reaction to cancer could be strengthened." (PMID 40692786, 2025). "CD164 was shown to regulate the proliferation, adhesion, and differentiation of hematopoietic stem cells, and accumulating evidence indicates its potential value as an investigative marker of tumorigenesis and stemness in different cancer types." (PMID 31007847, 2019). "From the results, we speculated that CD164 was a tumor promoter which could promote the progression of several carcinomas possibly by regulating CXCR4 relevant proteins and activating CXCR4/AKT signaling pathway." (PMID 30022623, 2018). "Because complicated regulatory networks controlled stemness and cellular plasticity in cancer stem cells, whether CD164 expression might directly promote MET remained to be investigated." (PMID 28903328, 2017). "While the role of CXCR4 in regulating migration of EWS cells has been previously established, there are no data at the moment supporting the role of CD164 in modulating EWS cancer cells motility." (PMID 32719743, 2020). "Hence, we investigated whether CD164 also induced SDF-1α production, and our ELISA data revealed more SDF-1α production in hOSE-CD164 cells and the cells isolated from the peritoneal xenografted tumor cells than in the other cancer cell lines." (PMID 24094005, 2013).
cancer (continued). "However, future studies of circulating basophils in cancer may benefit from the inclusion of additional markers for basophil identification (such as CD203c, CD123, and CRTH2), and basophil activation (such as CD203c, CD107a, CD13, CD164, CD69, and histamine or tryptase release)." (PMID 32645919, 2020).